TRAV6 (T cell receptor alpha variable 6)
Description:
V region of the variable domain of T cell receptor (TR) alpha chain that participates in the antigen recognition. Alpha-beta T cell receptors are antigen specific receptors which are essential to the immune response and are present on the cell surface of T lymphocytes. Recognize peptide-major histocompatibility (MH) (pMH) complexes that are displayed by antigen presenting cells (APC), a prerequisite for efficient T cell adaptive immunity against pathogens. Binding of alpha-beta TR to pMH complex initiates TR-CD3 clustering on the cell surface and intracellular activation of LCK that phosphorylates the ITAM motifs of CD3G, CD3D, CD3E and CD247 enabling the recruitment of ZAP70. In turn ZAP70 phosphorylates LAT, which recruits numerous signaling molecules to form the LAT signalosome. The LAT signalosome propagates signal branching to three major signaling pathways, the calcium, the mitogen-activated protein kinase (MAPK) kinase and the nuclear factor NF-kappa-B (NF-kB) pathways, leading to the mobilization of transcription factors that are critical for gene expression and essential for T cell growth and differentiation. The T cell repertoire is generated in the thymus, by V-(D)-J rearrangement. This repertoire is then shaped by intrathymic selection events to generate a peripheral T cell pool of self-MH restricted, non-autoaggressive T cells. Post-thymic interaction of alpha-beta TR with the pMH complexes shapes TR structural and functional avidity.
Synonyms: TCRAV5S1; TCRAV6S1
Gene: T-cell receptor variable (V) gene on chromosome 14 (21,768,489 to 21,769,080, forward strand). Ensembl gene ENSG00000211780.
Subcellular location: Cell membrane
Gene Ontology:
Biological process: response to bacterium
Cellular component: plasma membrane
Homologues: Orthologues: pig TRAV6 (51% identical). Paralogues in human: TRAV17 (45% identical), TRAV20 (39% identical), TRAV10 (37% identical), TRAV21 (37% identical), TRAV39 (36% identical), TRAV27 (34% identical), TRAV13-1 (33% identical), TRAV34 (32% identical), TRAV7 (32% identical), TRAV24 (31% identical), TRAV25 (30% identical), TRAV5 (30% identical), and 11 more.